CXCL10 (C-X-C motif chemokine ligand 10)
Diseases named in the same sentence as CXCL10 in open-access papers (continued):
Sharing a sentence is not in itself a finding about the gene and the disease.
COVID-19 (continued). "Among these genes are CD14, CSF2, and CXCL10, which are linked to COVID-19 related cytokine storm (CD14 and CXCL10) and acute respiratory syndrome (ARDS) (CSF2/GM-CSF)." (PMID 36980301, 2023). "This study emphasizes the association between CXCL9, CXCL10, CXCL11, and CXCR3 levels and disease severity in patients with COVID-19." (PMID 37493737, 2023). "Severe COVID-19 patients had elevated levels of cytokines, IL-6, CXCL-10, and HGF compared to mild/moderate." (PMID 37685858, 2023). "The severe COVID-19 risk allele for signal-B at TYK2 is associated with reduced SERPING1 and CXCL10 protein expression, implying that the minor allele at signal-B in the TYK2 locus reduces some aspect of TYK2 function." (PMID 36327221, 2022). "High-throughput and ultrasensitive proteomics platforms showed that the serum of cytokines and chemokines such as CCL8 and CXCL10 in COVID-19 patients was significantly higher than in healthy controls." (PMID 35747501, 2022). "We thus demonstrated that levels of plasma sFasL and T cell death correlate with the level of CXCL10, a marker of COVID-19 severity." (PMID 35066575, 2022). "In children, epithelial cell proportions did not change but in the immune compartment IL6+ monocytes were significantly enriched in COVID-19, with a trend towards higher CXCL10+ monocytes and neutrophils." (PMID 34937051, 2022). "In contrast, we observed lower CXCL10 concentrations in pregnant COVID-19+ patients than in NP-COVID-19+ patients." (PMID 35901034, 2022). "This identification assisted in exploring the co-expressed genes of TMPRSS2 and CXCL10 responsible for prostate cancer and COVID-19 development by utilizing the TCGA data." (PMID 36239108, 2022). "For this reason, among others, some authors have tried to find a relationship between the concentration of CXCL10 and IL-6 in COVID-19 patients." (PMID 35409036, 2022). "In terms of CXCL10, 4,549 genes happened to co-express with prostate cancer development while those with COVID-19 were 7,230." (PMID 36239108, 2022). "Similar to other respiratory diseases, high CXCL10 levels in COVID-19 patients showed a strong correlation with disease severity." (PMID 36366543, 2022). "The level of CXCL10 differs also according to the severity of disease, being 100% higher in severe when compared to milder cases of COVID-19." (PMID 35409036, 2022). "Proteomic analysis highlighted a cytokine storm in the serum of patients with COVID-19, with elevated expression levels of IL-6, CXCL10, CXCL11, IFNγ, MCP-2, and MCP-3 detected in infected patients relative to healthy controls." (PMID 35303909, 2022). "We found that the most profound changes were in MX-1 and CXCL10 expression, which are key in COVID-19." (PMID 36143354, 2022). "The concentrations of granulocyte colony-stimulating factor (G-CSF), IL-2, IL-7, IL-10, TNF, and the chemokines, CCL2, CCL3, and CXCL10 were extremely high in the plasma of patients with severe COVID-19." (PMID 36294868, 2022). "Plasma levels of IL-1RA, IL-10, IL-15, and G-CSF and of the chemokines CCL3, CCL4, CXCL8, and CXCL10 were significantly increased in patients with COVID-19 compared with those of healthy controls." (PMID 34793331, 2022). "It was also observed that CXCL10 concentration was seven times higher in severe and almost four times higher in mild/moderate courses of COVID-19 in comparison to healthy controls." (PMID 35409036, 2022). "Targeted analysis of fecal metabolites showed significantly lower fecal concentrations of SCFAs in COVID-19 patients, which correlated with disease severity and increased plasma concentrations of CXCL-10 and CRP." (PMID 35956081, 2022). "Altogether, the imbalance between pro-inflammatory CXCL10 and impaired capacity for biosynthesis of anti-inflammatory SCFAs or L-isoleucine is probably an important factor affecting the COVID-19 severity." (PMID 35409036, 2022). "This early humoral response was negatively correlated with the age of COVID-19 patients and plasma CXCL10 levels." (PMID 36030261, 2022).
COVID-19 (continued). "Severe cases of COVID-19 develop cytokine storms characterized by excessive systemic release of multiple cytokines including IP-10 (CXCL10), IL-6, IL-8 (CXCL8), and IL-10." (PMID 35247068, 2022). "To interpret the functional activity of TMPRSS2 and CXCL10 in prostate cancer and COVID-19, we used the set of previously determined co-expressed genes while using the PANTHER database." (PMID 36239108, 2022). "More importantly, our results highlighted that levels of CXCL10 correlated positively with the age of COVID-19 patients requiring ICU admission (r = 0.5483, p < 0.0009)." (PMID 36030261, 2022). "In particular, CXCL10 exhibits a persistent elevated expression pattern in COVID-19 patients, while in patients with other viral infections only a transient expression is observed (Buszko and others 2021)." (PMID 35647937, 2022). "In conclusion, we showed that patients with NAFLD have a different immune response to severe COVID-19, with IL-6, IL-8, IL-10, and CXCL10 as a possible culprits of an uncontrolled inflammation associated with disease severity in this group of patients." (PMID 35743825, 2022). "They observed that dexamethasone has a specific therapeutic effect on COVID-19 by regulating the CXCL10 and CXCR3 axis." (PMID 35409036, 2022). "Removal of patients with COVID-19 from this viral group resulted in fewer significantly different biomarkers: only CXCL10 was higher in the viral group, while both PDGFs and P-selectin were most increased in the bacterial group." (PMID 35660785, 2022). "CSA treatment was associated with significant reductions in serum cytokines and chemokines important in COVID-19 hyperinflammation, including CXCL10." (PMID 35536669, 2022). "Afterward Venn diagrams were contrived using the Bioinformatics and Evolutionary Genomics web tool in order to show the lists representing common co-expressed genes of TMPRSS2 and CXCL10 in each of the cases of prostate cancer and COVID-19." (PMID 36239108, 2022). "While responses were not different between bamlanivimab- treated individuals and those who received placebo, CCL2, CCL19, CCL20, CXCL8 and CXCL10 were upregulated in samples from the nasopharyngeal cavity and the circulating blood of patients with COVID-19." (PMID 35303909, 2022). "A similar pattern of upregulated proteins, especially chemokines such as CXCL10, and cytokines such as IL-6, is seen in the airways during acute COVID-19." (PMID 35151371, 2022). "Using miRNA profiling to deconvolute CC abundance resulted in identifying sets of miRNAs that correlate in a severity-specific manner with CC already associated with COVID-19 severity such as IL6 and CXCL10." (PMID 34957382, 2022). "In the COVID-19 pathway, the CXCL10 chemokines were highly downregulated in the low dose group by over 2.56-fold." (PMID 35854219, 2022). "We found that fatal COVID-19 was associated with higher levels of IL6, IL10, IL22, CXCL10, CCL2, and CCL20 and lower levels of miR-495-3p, miR-451a, and miR-29b-3p." (PMID 34957382, 2022). "In another clinical investigation, COVID-19 patients requiring ICU admission exhibited higher levels of CXCL10, CCL2, CCL3, and CCL7 compared to mildly infected patients." (PMID 36016187, 2022). "In this regard, symptomatic COVID-19 patients showed higher levels of CXCL10 compared with convalescent cases." (PMID 36366543, 2022). "Analysis of 48 cytokines in the plasma of 50 COVID-19 patients showed that CXCL10 is an important biomarker for disease severity, and its increase was associated with an elevation in CCL7 (monocyte-chemotactic protein 3 (MCP3))." (PMID 35062368, 2022). "This review describes the potential role of CXCL10 in the pathogenesis of COVID-19, as well as its potential immune–therapeutic significance." (PMID 35409036, 2022). "CXCL10 levels differ also according to the severity of the disease and they is the highest in critically ill patients with COVID-19." (PMID 35409036, 2022).
COVID-19 (continued). "Similar to dengue, those who proceed to develop severe COVID-19 have high levels of many proinflammatory cytokines such as IL-6, IL-1β, IL-10, CXCL-10, MCP-1 and the cytokine storm is shown to associate with both severe dengue and COVID-19." (PMID 35786403, 2022). "COVID-19 is characterized by inflammation, in which the expression of CXCL10 correlates with disease severity." (PMID 35066575, 2022). "CXCL10 reported at the time of hospital admission in COVID-19 patients is the best prognostic indicator of fatality amongst 52 other possible biomarkers related to viral infection." (PMID 36614003, 2022). "For example, severe COVID-19 was linked to changes in IL-13, IL6 and IL-1B, and multiple chemokines (e.g. CCL20, CCL27, CXCL10)." (PMID 36171541, 2022). "The studies are evidence that show that production of CXCL10, with a high probability, increases the progression of COVID-19." (PMID 35409036, 2022). "Circulating levels of other monocyte/macrophage chemotactic factors are elevated in blood and/or BAL fluid in COVID-19 (GM-CSF, CXCL10, and MCP-1) and positively correlate with disease severity." (PMID 34710339, 2022). "Upregulation of CXCL10, the ligand of CXCR3, is associated with COVID-19 severity promoting chemoattraction via CXCR3 for activated lymphocytes and monocytes." (PMID 36238301, 2022). "The COVID-19 risk allele (T), that correlates with increased TYK2 transcript expression, correlated with reduced amounts of SERPING1 and CXCL10 proteins in plasma (p = 0.0003)." (PMID 36327221, 2022). "CXCL10 and CCL2 are biomarkers that have been associated with disease severity and the risk of death in COVID-19 patients." (PMID 35958594, 2022). "High levels of chemokines were also detected in severe forms of COVID-19: IFN-induced proteins-10 (IP-10/CXC-chemokine ligand 10 (CXCL10)), CXCL9, monocyte chemoattractant protein-1 (MCP1), chemokine ligand-2 (CCL)-2 and IL-8." (PMID 36560410, 2022). "Elevated serum levels of CXCL10 found in COVID-19 patients are positively correlated with increased disease severity and, more importantly, with an increased risk of mortality as seen in our results above." (PMID 36286038, 2022). "They showed that IL-6, CCL2, CXCL8, CXCL9, and CXCL10/IP10 levels were higher in patients with MIS-C than in those with COVID-19." (PMID 35268506, 2022). "We discovered that TMPRSS2 and CXCL10 are overexpressed in prostate cancer and COVID-19 using the UALCAN and GEPIA2 datasets." (PMID 36239108, 2022). "The Described study is in accordance with previous findings focusing on the role of TLR7 and CXCL10, which is directly associated with TLR7 in severe course of COVID-19." (PMID 35409036, 2022). "The percentage of activated (CD69+) total ILCs and activated ILCp positively correlated with serum IL-6 levels and with CXCL10 levels in the COVID-19 patients." (PMID 35159352, 2022). "Several chemokines linked to COVID-19 were also significantly induced by the S1 subunit, including CCL3/MIP-1α, CCL4MIP-1β, and CXCL10/IP-10." (PMID 35392091, 2022). "Our data also confirm the role of CCL2 and CXCL10 in severe COVID-19 as these chemokines were found to be increased in serum of patients admitted to ICU." (PMID 35386707, 2022). "Similar results were obtained by other scientists who observed that patients with severe courses of COVID-19 have significantly elevated concentrations of CXCL10." (PMID 35409036, 2022). "Comparative analysis of COVID-19 patients according to Discharge or Death outcome demonstrated that the latter presented higher IL-6 and CXCL10 levels at corresponding timepoints." (PMID 36451835, 2022). "IL-15, CCL8, and CXCL10 levels were also significantly elevated in the BAL fluid of patients with COVID-19 in the mid- or late phase of a coinfection compared with patients without coinfections." (PMID 34793331, 2022).
COVID-19 (continued). "CXCL10 is a notable cytokine, which has been found in elevated levels in both cancer and COVID-19 patients, driving metastasis, inflammation and poor clinical outcomes in both the cases." (PMID 36239108, 2022). "In this study, in individuals with COVID-19, CXCL10 levels were higher than in healthy controls and the same is true after age adjustment." (PMID 35958594, 2022). "Consistent with prior studies, we found that IL-6, IL-8, IL-1RA, CXCL-10 distinguished healthy controls from both moderate and severe COVID-19 cases." (PMID 35421120, 2022). "Data analysis demonstrated that COVID-19 patients presented a clear pro-inflammatory storm, mediated by IL-6 and CXCL10 with the highest magnitude order (≥19x; ≥10x, respectively)." (PMID 36451835, 2022). "Within our COVID cohort, nonsurvivors were characterized by higher cytokine levels, especially IL-1RA, IL-6, MCP-1, CXCL8, and CXCL10 than patients who survived COVID-19." (PMID 35359931, 2022). "Of note, Ccl8 and Ccl2 as well as Cxcl9 and Cxcl10, chemoattractants for monocytes and T cells, respectively, were significantly up-regulated in the lungs of AR-infected mice and in COVID-19 patients, in line with the increased recruitment of these cells." (PMID 34812647, 2022). "The majority of upregulated cytokines and chemokines, such as IL-6, TNF, CCL2, CCL3, and CXCL10, have been reported to be associated with cytokine release syndrome (CRS), including MAS, in severe COVID-19 cases." (PMID 35440562, 2022). "In COVID-19 patients with severe disease (intubated), as compared to those with mild to moderate disease, the median CXCL10 concentration was twice as high." (PMID 34242356, 2021). "We also compared CXCL-10 levels in the 43 COVID-19 patients from Pakistan stratified by disease severity using an in-house assay developed by us." (PMID 34242356, 2021). "At this time, the disease COVID-19 clinically manifests itself and early markers of the innate immune response such as CXCL10 are detectable." (PMID 33643932, 2021). "In post-COVID-19 subjects, the cytokine production of monocytes was similar to that of HC, except for CXCL10, which was synthesized significantly less than in HC." (PMID 34572439, 2021). "From the Comparative Toxicogenomics Database (CTD), we retrieved the most significant 15 proteins which have a direct association with the COVID-19 disease development where ACE2 and CXCL10 proteins are also included." (PMID 33585826, 2021). "We recently identified a unique cytokine response in COVID-19 patients with severe pneumonia with higher plasma GM-CSF and CXCL10 (a Th-1 chemokine) in COVID-19 patients, that were independently associated with the longer duration of mechanical ventilation." (PMID 34031519, 2021). "This study suggests that CCL2 and CXCL10 have the potential to be used as anti-inflammatory targets for COVID-19 therapy." (PMID 35002688, 2021). "When considering the pathological increased serum CXCL-10 levels reported in COVID-19 patients, therapeutics inhibiting these axes by IFN-γ antagonism represent a very promising strategy." (PMID 33445810, 2021). "Plasma proteins associated with neutrophil and ROS responses including IL8, CXCL10, and EN-RAGE primarily derived from activated neutrophils, IL6, and PRDX1 were also elevated in lung tissue from patients with COVID-19." (PMID 34648357, 2021). "It is worth to mention, CXCL10 was reported to be correlated with the severity and progression of COVID-19 recently." (PMID 34481469, 2021). "The strongest upregulation was observed for CXCL10 with a mean of around 4 500 pg/mL in COVID-19 against around 5 pg/mL in healthy sample." (PMID 34386007, 2021). "These commonly co-expressed genes were utilized to interpret the functional nature of ACE2 and CXCL10 both in lung cancer and COVID-19 development." (PMID 33585826, 2021). "On the other hand, 2088 genes were identified which are co-altered along with the expression of CXCL10 in both cases of lung cancer and COVID-19." (PMID 33585826, 2021).
COVID-19 (continued). "We demonstrated that the CXCL10+ CCL2+ macrophages from severe COVID-19 lungs share a transcriptional phenotype with macrophages stimulated by TNF-α plus IFN-γ." (PMID 33879239, 2021). "Similar results in the progressive decline of plasma concentrations of CXCL-10 with positive patient outcome has been reported in COVID-19 by others, and in TB patients by our group." (PMID 34242356, 2021). "The median CXCL-10 concentration in severe and mild to moderate COVID-19 patients compared to healthy individuals was 7 and 3.8-fold higher, respectively." (PMID 34242356, 2021). "We detected the gene signature for the CXCL10+ CCL2+ inflammatory macrophage state in a higher proportion of macrophages from severe COVID-19 BALF than from other inflamed tissues." (PMID 33879239, 2021). "In particular, the cytokines IL-6, IL-8, CXCL9, and CXCL10 (IP-10) were identified as putative prognostic disease progression markers for COVID-19." (PMID 34759825, 2021). "CXCL10 was recently identified as the cardinal chemokine playing a crucial role in COVID-19 being a chemoattractant for monocytes/macrophages, dendritic cells, NK cells, and T cells." (PMID 33981314, 2021). "The median concentration of CXCL-10 in plasma samples in severe COVID-19 patients was 2-fold higher than mild to moderate COVID-19 patients, however, the difference was not statistically significant (p-value = 0.3931)." (PMID 34242356, 2021). "Their results revealed host inflammatory cytokine profiles to SARS-CoV-2 infection in patients and highlighted the association between COVID-19 pathogenesis and excessive cytokine releases such as CCL2/MCP-1, CXCL10/IP-10, CCL3/MIP-1A, and CCL4/MIP1B." (PMID 34441862, 2021). "This is supported by the potential utility of CXCL10 as an early prognostic marker of COVID-19 severity." (PMID 33692097, 2021). "Collectively, these findings are consistent with the elevated plasma levels of inflammatory markers observed in COVID-19 patients, where the profile of IL-6, CCL2/MCP-1, and CXCL10/IP-10 are associated with the severity of the disease." (PMID 34572407, 2021). "Among those studies, a paper published on Nature Biotechnology identified that critical COVID-19 cases had shown stronger interactions between epithelial and immune cells which includes inflammatory macrophages expressing CXCL10." (PMID 34109284, 2021). "In consistence with previous observations, IL-6, CCL2, CXCL2, CXCL10, and IL-8 were significantly elevated in COVID-19 samples." (PMID 34103487, 2021). "Levels of IFN-α2a and the IFN-inducible chemokine CXCL10/IP-10 were significantly induced in the blood of COVID-19 patients across all severity groups." (PMID 33232303, 2021). "CXCL-10 levels were significantly elevated in both severe and mild/moderate COVID-19 cases compared to healthy controls (*** p<0·001 and * p<0.05 respectively)." (PMID 34242356, 2021). "From here, we explored the co-expressed genes of ACE2 and CXCL10 responsible for lung cancer and COVID-19 development by utilizing the TCGA data." (PMID 33585826, 2021). "The limited data suggests that COVID-19 pregnancies have similar elevations of cytokines (IL-6, TNFα) and chemokines (CCL2, CXCL10) as other COVID-19 patients." (PMID 33168125, 2021). "To interpret the functional activity of ACE2 and CXCL10 in lung cancer and COVID-19, we used the lists of previously identified co-expressed genes using the PANTHER database." (PMID 33585826, 2021). "We found that the antiviral immune mediator and leukocyte recruitment factor CXCL10 and the myeloid cell growth factor GM-CSF were strikingly elevated in fatal cases of COVID-19." (PMID 33692097, 2021). "After that, the lists representing co-expressed genes of ACE2 and CXCL10 in each of the cases of lung cancer and COVID-19 were utilized to construct Venn diagrams using the Bioinformatics and Evolutionary Genomics web tool." (PMID 33585826, 2021).